TEP1 (telomerase associated protein 1)
Diseases named in the same sentence as TEP1 in open-access papers (continued):
Sharing a sentence is not in itself a finding about the gene and the disease.
tumor (15 papers, 2012 to 2025). "The tumor suppressor PTEN/MMAC1/TEP1 is known to be a regulator of cellular processes like cell proliferation, migration, motility and apoptosis, being frequently mutated in tumor cells." (PMID 29954386, 2018). "Instead, it functions as a tumor suppressor by competitively binding to TEP1." (PMID 40583858, 2025). "Thus, the research and results link the markers regulating the tumor process and the telomerase complex TEP1 rs1760904, rs1713418, TERC rs12696304, rs35073794, TERT rs2736098, rs401681, which help explain the factors leading to the development of telocytes." (PMID 35892421, 2022). "The CLS phenotype of yeast Tep1 and its association to other phosphatidylinositol proteins provide a simple model system to elucidate the molecular mechanisms underlying the role of its mammalian homologue PTEN in embryonic survival and tumor suppression." (PMID 24586198, 2014). "Tu42 cells did not express PTEN/MMAC1/TEP1 in vitro; however, PTEN/MMAC1/TEP1 expression could be detected in Tu42 cell-derived tumor xenograft, indicating reversible PTEN/MMAC1/TEP1 loss in these cells." (PMID 31013771, 2019). "In vivo, circMAN1A2 overexpression suppressed tumor growth, enhanced TMZ sensitivity, and reduced NRF2/ANXA1 expression, effects reversed by TEP1." (PMID 40583858, 2025). "The result showed that the expression of REEP3, REEP4, TEP1, and EEPD1 was significantly higher in GBM tumor tissue." (PMID 37818043, 2023). "The GEPIA and TCGA datasets were used to analyze the expression patterns of REEP3, REEP4, TEP1, and EEPD1 in tumor tissue and normal tissue." (PMID 37818043, 2023). "To evaluate REEP3, REEP4, TEP1 and EEPD1 mRNA levels in multiple tumor and normal samples, we downloaded and compiled data from 11124 samples (Tumor =7260, Normal =3864) from the TCGA database." (PMID 37818043, 2023). "REEP3, REEP4, TEP1 and EEPD1 was differentially expressed in 14, 17, 14, 13 tumor types, respectively." (PMID 37818043, 2023). "As shown in, the REEP3, REEP4, TEP1, and EEPD1 had significantly higher expression in GBM tumor tissues compared to normal tissues." (PMID 37818043, 2023). "Fittingly, in our study, TNFα was a strong stimulator of vault RNA, MVP, and TEP1 gene expression and also MVP protein expression in the TNFα-responsive BON tumor model." (PMID 36980669, 2023). "Human CDC14A shares sequence similarity with the recently identified tumor suppressor, MMAC1/PTEN/TEP1." (PMID 22548743, 2012).
bacterial infections (3 papers, 2012 to 2017). "In fact, experimental infections demonstrated that laboratory-reared A. gambiae individuals homozygous or heterozygous for TEP1*R1 and TEP1rB alleles are significantly more resistant to Plasmodium and bacterial infections than mosquitoes carrying other TEP1 alleles." (PMID 26047479, 2015). "The knockdown of either TEP1 or CLIPA8 abolished hemolymph PO activity in response to bacterial infections, indicating a tight control by TEP1 over the melanization response." (PMID 28928218, 2017). "TEP1 is known to be an important anti-bacterial factor, which raises the possibility that the rapid death observed in fungal infected TEP1 kd mosquitoes could be due to the proliferation of opportunistic bacterial infections rather than fungal proliferation." (PMID 23166497, 2012).
TEP1 also shares sentences with these, for which no sentence is quoted: Cirrhosis (2 papers); age-related macular degeneration (1); astrocytoma (1); Azoospermia (1); bone osteosarcoma (1); cardiovascular disease (1); cryopyrin-associated periodic syndrome (1); Desminopathy (1); endometrial cancer (1); gram-negative bacterial infections (1); hepatocellular carcinoma (1); Huntington disease (1); hyperinsulinism (1); ischemic stroke (1); liver diseases (1); melanoma (1); multiple sclerosis (1); myocardial infarction (1); neurological disorders (1); Parkinson (1); psoriasis (1); renal cell carcinoma (1); schistosomiasis (1); schizophrenia (1); type 2 diabetes (1); urothelial cell carcinoma (1).